DOT1L (DOT1 like histone lysine methyltransferase)
Diseases named in the same sentence as DOT1L in open-access papers (continued):
Sharing a sentence is not in itself a finding about the gene and the disease.
leukemia (continued). "Furthermore, a few recent publications have reported that DOT1L plays crucial roles not only in leukemia, but also in solid tumors, such as breast cancer, esophageal squamous cell carcinoma, colorectal cancer, prostate cancer, and gastric cancer." (PMID 28114995, 2017). "Consistent with DOT1L loss-of-function studies, these DOT1Li also selectively inhibited expression of MLL-fusion target genes such as HOXA9 and MEIS1 and selectively killed MLL-rearranged leukemia cells and xenografted tumors." (PMID 29075615, 2017). "Therefore, medicinal chemistry efforts for DOT1L inhibition have led to the first HMTi in clinics, compound that completed phase I clinical trials for leukemia treatment and myelodysplastic syndromes (NCT02141828, NCT01684150)." (PMID 28067760, 2017). "In addition, DOT1Li and BRDi are shown to be synergistic in treating MLL-rearranged leukemia, possibly due to functional collaboration between DOT1L and BRD4 at the highly transcribed super-enhancer genes." (PMID 29075615, 2017). "DOT1L plays a crucial role in various physiological and pathological processes, like transcriptional regulation, cell-cycle regulation, DNA repair, embryonic development, hematopoiesis, cardiac function, and leukemia development." (PMID 27222667, 2016). "Interestingly, BET inhibitors and DOT1L inhibitors are also effective in vitro in a variety of other leukemias and hematologic malignancies such as multiple myeloma or Burkitt lymphoma, for which HOXA or c-myc activation are key drivers of the disease." (PMID 27723796, 2016). "A potent DOT1L inhibitor has been in clinical trials against MLL-rearranged leukemia." (PMID 26970896, 2016). "Our observation that treatment of SEM cells with DOT1L inhibitors appears to cooperate with ABT-199 treatment provides an interesting proof of principle that DOT1L inhibitors could potentially be used to sensitize MLLr leukemias to treatment with ABT-199." (PMID 26711339, 2015). "Indeed, several other DOT1L inhibitors have been reported to induce apoptosis of MLL-rearranged leukemia cell lines." (PMID 24858818, 2014). "However, the requirement for H3K79-methylation-dependent gene overexpression in MLL-rearranged leukemia rendered these cells far more sensitive to DOT1L inhibitors." (PMID 24858818, 2014). "Further, DOT1L inhibitors may be combined with other DNA-damaging anticancer drugs to reverse chemoresistance of MLL-rearranged leukemia cells." (PMID 24858818, 2014). "Therefore, it is possible that inhibition of DOT1L by SYC-522 sensitized MLL-rearranged leukemia cells to chemotherapy by disrupting DNA damage signaling and preventing DSB repair." (PMID 24858818, 2014). "In AML with recurrent mixed lineage leukemia (MLL) gene translocation resulting in aggressive leukemias, DOT1L is aberrantly recruited to MLL target genes via interaction with the MLL translocation product where the expression of these genes also requires DOT1L histone methyltransferase activity." (PMID 24840099, 2014). "Next, we tested whether SYC-522 inhibited the expression of MLL-fusion target genes HOXA9 and MEIS1, both of which have been found to be overexpressed in MLL-rearranged leukemia and downregulated by treatment with a DOT1L inhibitor." (PMID 24858818, 2014). "In addition, our findings supported the conclusion that DOT1L is important for drug resistance of MLL-rearranged leukemia." (PMID 24858818, 2014). "Since DOT1L methyltransferase activity is critical to MLL-rearranged leukemia, inhibition of DOT1L may provide a potential therapy for this type of leukemia." (PMID 24858818, 2014). "In summary, our results suggested that DOT1L inhibition may be a potent strategy for the treatment of MLL-rearranged leukemia by inhibiting DOT1L methyltransferase activity and its downstream targets, thereby promoting differentiation." (PMID 24858818, 2014). "These DOT1L inhibitors also exhibit selective activity against MLL-rearranged leukemia." (PMID 25359765, 2014).
leukemia (continued). "DOT1L is a drug target for mixed lineage leukemia (MLL) gene rearranged leukemia." (PMID 25359765, 2014). "Methylation of H3K79 is catalyzed by the disruptor of telomeric silencing proteins DOT1/DOT1L and plays an essential role in cell cycle regulation, embryonic development, DNA damage response, hematopoiesis, cardiac function, and the development of leukemia." (PMID 25215303, 2014). "Recently the possibility has arisen that MLL-R leukemia may be targeted by blocking ubiquitinylation of histone 2B, preventing activation of DOT1L." (PMID 23847761, 2013). "If human DOT1L plays similar roles in mammals, mistargeting of DOT1L in human leukemia might antagonize gene silencing or repression, and thereby lead to higher gene expression levels." (PMID 21291527, 2011). "Notably, DOT1L is strongly correlated with MLL‐rearranged leukemia." (PMID 39307938, 2024). "Thus, the MOZ/MORF KAT inhibitor and its combination with DOT1L KMT inhibitors may provide novel therapeutic strategies for this malignant subtype of leukemia." (PMID 37031220, 2023). "Notably, the HMTase activity of DOT1L is an important driver in most MLL-rearranged leukemias." (PMID 37051671, 2023). "Thus, the combination therapy with MOZ/MORF KATs and DOT1L KMT inhibitors could improve therapeutic outcomes in AF10 translocation-induced leukemia." (PMID 37031220, 2023). "Therefore, DOT1L has become a potential target for developing therapeutic drugs to treat leukemia." (PMID 35419278, 2022). "Therefore, PPIs between AHD and DOT1L or AF4/AFF4 are a potential drug target for MLL-r leukemia." (PMID 34373735, 2021). "Therefore, DOT1L inhibition attained by pinometostat as a stand-alone therapy is not sufficient to achieve clinical benefit in patients with relapsed/refractory MLL-r leukemia." (PMID 34698191, 2021). "The pronounced sensitivity of the FLT3-ITD/STAT5A signaling axis to DOT1L inhibition raises the possibility that non-MLL-rearranged leukemias with FLT3-ITD mutations, representing 30–40% of acute myeloid leukemias, may also be susceptible to DOT1L inhibition." (PMID 34263728, 2021). "To investigate whether the R domain mediates the response of MLL-AF9 leukemia cells to DOT1L-inhibitory treatment, we compared a pair of pooled survival tiling screens conducted under control (dimethyl sulfoxide (DMSO)) vs. DOT1L-inhibited (1 μM EPZ5676) conditions." (PMID 34210975, 2021). "Therefore, further study of the DOT1L biology in MLL leukemias could offer alternative strategies to inhibit the acquired self-renewal in MLL leukemia stem and progenitor cells by targeting DOT1L pathways." (PMID 32552847, 2020). "Thus, the identification and understanding of specific regulators of DOT1L in MLL leukemia could provide a precise target to block MLL leukemia cell stemness." (PMID 32552847, 2020). "Importantly, DOT1L also plays a pivotal role in tumors, especially leukemia and thymic lymphoma." (PMID 31888761, 2019). "Furthermore, disruption of SAM/Met metabolism, especially by dietary restriction, may be an immediate alternative strategy to improve SOC chemotherapy outcomes in patients with MLL-R leukemia, as DOT1L inhibitors have yet to be FDA approved and mass produced." (PMID 31717699, 2019). "Given the dependence of the dual H3K36me3-H3K79me2 signature across MLL-target genes on SETD2 and the strong requirement of MLL-leukemia for the H3K79 methyltransferase DOT1L21, we reasoned that SETD2 loss might cooperate with pharmacologic inhibition of DOT1L." (PMID 29777171, 2018). "Similarly, the other gene activating factors might also be involved along with DOT1L since DOT1L is known to function in coordination with MLL2 for maintenance of gene expression in leukemia." (PMID 29631608, 2018).
leukemia (continued). "Often, the leukemia-associated MLL gene rearrangement produces the MLL fusion oncoprotein that loses MLL’s C-terminal SET domain and gains a partial sequence from its fusion partner such as AF4, AF9, AF10, or ENL, which recruits the DOT1L-associated transcription elongation complexes." (PMID 29075615, 2017). "Consequently, DOT1L is a drug target for MLL-rearranged leukemia." (PMID 28114995, 2017). "Interestingly, MLL-AF6 leukemias remain sensitive to DOT1l inhibitors." (PMID 27007052, 2016). "In MLL-rearranged leukemia, the MLL-AF9 fusion protein aberrantly recruits transcriptional and epigenetic modifiers, including DOT1L, BCOR, and CBX8, disrupting normal hematopoietic gene regulation." (PMID 42063817, 2026). "DOT1L and Menin are essential cofactors for the oncogenic activity of MLL fusion proteins (MLL-FPs) in leukaemia." (PMID 41634341, 2026). "In mixed lineage leukemia (MLL)-rearranged leukemia, MLL fusion proteins interact with DOT1L and transcriptionally activate target oncogenes that drive leukemia development." (PMID 41299712, 2025). "DOT1L inhibitors thus exert selective and strong anti-tumor effects against MLL-rearranged leukemia." (PMID 41299712, 2025). "For example, the H3K79 methyl transferase DOT1L and Menin, which interacts with MLL in conjunction with the H3K36 me2/3 reader LEDGF, have been shown to be especially important for MLL-AF9 leukemia." (PMID 39450904, 2025). "DOT1L, which is a histone H3K79 methyltransferase, promotes oncogenic transcription in leukemia and solid tumors (including PCa) by maintaining H3K79me2 at proliferative genes." (PMID 40297177, 2025). "Another DOT1L inhibitor, EPZ-5676, showed promising results in a phase I clinical trial in MLL-rearranged leukemia and was validated as ‘orphan drug’ toward MLL-rearranged leukemia by FDA." (PMID 38681199, 2024). "DOT1L inhibitors have also been found to synergize with MI-2-2, MI-503, and VTP50469 in MLLr and NPM1 mutant leukemias, with combination treatment resulting in a more significant increase in differentiation compared to MI alone." (PMID 39336822, 2024). "Along with its interaction with MLL, menin can also promote leukemia through its interactions with PSIP1, c-Myb, and DOT1L." (PMID 39336822, 2024). "The discovery of DOT1L’s contribution to cancer progression, particularly in the context of MLL-rearranged leukaemia, was monumental to the field." (PMID 38962004, 2024). "MLL fusion partner proteins, such as AF10, AF9, and eleven nineteen leukemia (ENL), interact directly with DOT1L, which plays a role in the overactivation of MLL target genes through H3K79 methylation." (PMID 39394462, 2024). "Inhibiting key players in the HBP or blocking O-GlcNAc transferase activity was demonstrated to increase cellular sensitivity to DOT1L inhibition, suggesting that targeting DOT1L degradation is a potential therapeutic strategy for MLL-fusion leukemia." (PMID 39394462, 2024). "Consistent synergy in halting cell proliferation has also been observed with EPZ-5676, a DOT1L inhibitor, and DNMT inhibitors in MLL-rearranged leukemia cell lines." (PMID 39766049, 2024). "We will discuss therapies targeting the singular H3K9 methyltransferase DOT1L and the H3K4 methyltransferase MLL1 next, as these have been or are now in clinical stages of development for the treatment of various leukemias." (PMID 39403928, 2024). "It is also reported that small‐molecule inhibition or genetic disruption of DOT1L and BRD4 shows significant synergistic activity against KMT2A‐r leukemia cell lines." (PMID 39428967, 2024). "DOT1L inhibitor EPZ5676 was trialled in pediatric and adult patients with KMT2Ar refractory or relapsed leukemia (NCT02141828 and NCT01684150 clinical trials)." (PMID 37325571, 2023). "LncRNA LAMP5-AS1 directly binds to methyltransferase DOT1L and promotes DOT1L-mediated H3K79 dimethylation and trimethylation of target genes involved in leukemia stem-cell proliferation." (PMID 37345170, 2023).
leukemia (continued). "As a transcriptional addiction gene, DOT1L-mediated transcriptional regulatory mechanisms were involved in developing and maintaining MLL leukemia." (PMID 37171044, 2023). "EPZ-5676, a DOT1L KMT inhibitor, had anti-proliferative effects on both P31/FUJ and MLL translocation-induced leukemia cell lines similar to those reported in previous studies in other disease models 37,38." (PMID 37031220, 2023). "Venetoclax was found to synergize with DOT1L inhibitors and is being evaluated in clinical trials for pediatric KMT2A-rearranged leukemias." (PMID 37740239, 2023). "AdoMet-competitive DOT1L inhibitors selectively kill mixed lineage leukemia cells, prolong survival in a mouse xenograft model of MLL-rearranged leukemia and have been in clinical trials (e.g. Pinometostat)." (PMID 37051671, 2023). "Phase I clinical trial of Dot1l inhibitors such as EPZ-5676, a therapeutic agent for leukemia, has been completed." (PMID 36639782, 2023). "Pharmacological inhibition of DOT1L in cell line and xenograft models of KMT2A-r leukemia has shown anti-leukemic activity and restores normal HOXA and MEIS1 transcription." (PMID 38174649, 2023). "To confirm that the DOT1L inhibitors used were active, we analyzed a known DOT1L-dependent MLL-rearranged leukemia cell line (MV4-11) and a known DOT1L inhibitor insensitive T-cell leukemia cell line (Jurkat)." (PMID 36425063, 2022). "For this experiment the HDAC inhibitor Vorinostat, which is already approved for CTCL treatment, and the DOT1L inhibitor Pinometostat, which is in clinical trials for MLL-rearranged leukemia, were chosen." (PMID 36425063, 2022). "DOT1L, however, is dispensable for BCR-ABL, E2A-HLF, E2A-PBX2 leukemias, and leukemia generated by ectopic retroviral overexpression of HOXA9/MEIS1." (PMID 35712672, 2022). "Originally designed to hamper the progression of MLL-rearranged leukemia, a beneficial effect of EPZ004777 treatment was also observed for several solid malignancies, where DOT1L plays an important role." (PMID 35495127, 2022). "Recently, evidences of complementary activities of menin and DOT1L inhibitors in NPM1-mutant and MLL-rearranged leukaemia have been demonstrated." (PMID 36333801, 2022). "DOT1L inhibitor pinometostat(EPZ-5676) explored in Phase I clinical trials used to treat pediatric and adult patients with MLL-driven leukemia presented promising outcomes(NCT02141828)." (PMID 36376832, 2022). "By occupying the SAM-binding pocket and inducing conformational changes in DOT1L, EPZ-5676, a derivative of EPZ004777, is another effective DOT1L inhibitor that led to tumor regression in rat xenograft models of MLL-rearranged leukemia." (PMID 34050894, 2022). "SYC-522, a potent DOT1L inhibitor, was developed to inhibit the methylation at H3K79, decrease the expression of HOXA9 and MEISI and raise the sensitivity of MLL-rearranged leukemia cells presenting a potential means to treat MLL-rearranged leukemia." (PMID 36376832, 2022). "The anti-stemness cluster was enriched in epigenetic drugs or combinations targeting BET bromodomains (OTX015), menin-MLL interactions (MI-2), and DOT1L (EPZ-5676), which have demonstrated pre-clinical activity on the NPM1c leukemia-initiating program." (PMID 35750691, 2022). "This pathway also depends on MLL1, indicating combinations of DOT1L, MLL1 and FLT3 inhibitors should be explored for treating FLT3-mutant leukemia." (PMID 34263728, 2021). "Knowing that DOT1L primarily drives Hoxa9 and Meis1 expression for the initiation and maintenance of MLL-AF9 leukemia, we expected that with decreased H3K79me2, we would see a profound decrease in expression of MLL target genes." (PMID 33562706, 2021). "DOT1L has been found to be required for expression of MLL1-target genes such as HoxA9 and Meis1 and therefore a drug target for MLL1-r leukemia." (PMID 33823889, 2021). "During the past few years, potent inhibitors of DOT1L have been developed, showing potent and selective activities against MLL1-r leukemia." (PMID 33823889, 2021).
leukemia (continued). "Next, we assessed the impact of disrupting the DOT1L and AF9 interactions on H3K79 methylation in MLL-AF9 leukemia cells expressing wild type or mutant DOT1L." (PMID 33562706, 2021). "Another selective inhibitor of DOT1L, SYC-522, an S-adenosyl-L-methionine (SAM) derivative, blocks the cell cycle at the G0/G1 phase and sensitizes MLL-r leukemia cells to chemotherapeutic agents (mitoxantrone, etoposide, and cytarabine), causing apoptosis." (PMID 34698191, 2021). "Different from the leukemia mechanism of MLL gene translocation, DOT1L is also believed to play an important role in the occurrence and development of breast cancer." (PMID 34149432, 2021). "To further interrogate the H3K79me2-dependence of leukemia survival on FLT3-ITD/STAT5A signaling, we sought to ectopically restore this signaling pathway upon DOT1L inhibition to potentially rescue viability." (PMID 34263728, 2021). "Altogether, these data provide functional confirmation of the importance and critical role of DOT1L recruitment in MLL-AF9-driven leukemogenesis, validating these protein-protein interactions as a potential therapeutic target in MLL-rearranged leukemia." (PMID 33562706, 2021). "Co-IP showed that the inhibitor 1 dose-dependently reduced MLL-AF9-bound DOT1L and AF4 in Molm-13 leukemia cells, indicating it is cell-permeable and can disrupt the target PPIs in cells." (PMID 34373735, 2021). "DOT1L inhibition reduces STAT5A activation and downregulates STAT5A targets in FLT3-ITD leukemia lines." (PMID 34263728, 2021). "By targeting the MLL-AF9-DOT1L interaction, DOT1L recruitment is blocked, leading to inhibition of the growth of MLL-AF9-driven leukemia cells, selective downregulation of MLL-target gene expression by decreasing H3K79 methylation, followed by differentiation." (PMID 33562706, 2021). "Functionally, O-GlcNAcylation is important for DOT1L protein level in vivo and contributes to overactivation of critical oncogenes in MLL-fusion leukemia." (PMID 35201498, 2021). "Previous studies highlighted the role of DOT1L in the development and maintenance of mixed lineage leukemia (MLL)-rearranged leukemia." (PMID 34253709, 2021). "Profiling the targets of these compounds distinguishes certain KMT2Ar leukemias in which DOT1L is enriched at KMT2A fusion oncoprotein target sites, thus providing a strategy for selecting patients for whom treatment with DOT1L-targeting compounds is suitable." (PMID 34663924, 2021). "During the past few years, inhibitors of DOT1L have shown potent and selective activity against MLL1-r leukemia." (PMID 34698191, 2021). "Because DOT1L plays an important role in the development and maintenance of MLL-rearranged leukemia, EPZ-5676 has been used in several clinical trials for the treatment of the same." (PMID 34253709, 2021). "The aberrant transcriptional activation by methylation of H3K79 by DOT1L induces transcriptional activation and it is found aberrant in Mixed-Lineage Leukemias (MLL) rearranged leukemias (MLLr)." (PMID 34500733, 2021). "Depletion of this transcriptionally activating mark by DOT1L deletion or high concentrations of the inhibitor pinometostat downregulates HOXA9 and MEIS1, and consequently reduces leukemia survival." (PMID 34263728, 2021). "Combination treatment with EPZ004777, an inhibitor of H3K79 methyltransferase DOT1L, had more profound antitumor activity against MLL1-r leukemia." (PMID 33823889, 2021). "Consistently, pharmacological inhibition of DOT1L in combination with DNA-damaging agents further enhanced the growth inhibition of colorectal cancer cells and MLL-rearranged leukemia cells." (PMID 34887387, 2021). "Our observations suggest that most of the toxicity from low-dose DOT1L inhibition in MLL-r, FLT3-ITD+ leukemia cell lines stems from downregulation of FLT3 and subsequent loss of STAT5A phosphorylation." (PMID 34263728, 2021).